GFRA1 (GDNF family receptor alpha 1)
Diseases named in the same sentence as GFRA1 in open-access papers (continued):
Sharing a sentence is not in itself a finding about the gene and the disease.
Cognitive impairment (5 papers, 2019 to 2024). Abnormal cognition is characterized by deficits in thinking, reasoning, or remembering. "It seems reasonable to propose that decreased Gdnf and GFRα1 expression contributes to the intergenerational transmission of cognitive impairment." (PMID 37055728, 2023). "NBP was protective against hippocampal neuron apoptosis, and this was associated with regulation of GDNF/GFRα1/Ret and AKT/ERK1/2 signaling pathways, thus reducing cognitive impairment." (PMID 31456664, 2019). "Abnormalities in the structure and signaling of GFRα1 (GFRA1 gene) or RET (RET gene), caused by genomic variants or mutations within these genes, may also underlie various mental and cognitive disorders." (PMID 38646100, 2024). "Hence, in this study we preliminarily explored the relationship between Gdnf and GFRα1 expression and cognitive deficits, while controlling for interference from pro-inflammatory cytokines, in F1 and F2 offspring from LPS-treated gestating mouse dams." (PMID 37055728, 2023).
Parkinson disease (5 papers, 2017 to 2025). A progressive degenerative disorder of the central nervous system characterized by loss of dopamine producing neurons in the substantia nigra and the presence of Lewy bodies in the substantia nigra and locus coeruleus. "Given the function of GFRA1 in neuronal development, GFRA1 has been studied with eyes on the emerging therapeutic treatment in neuronal disease, especially Parkinson’s disease." (PMID 29617307, 2018). "Most studies of GDNF/GFRA1 signaling are related to neurodegenerative (Parkinson’s disease and Alzheimer’s disease) and neuropsychiatric diseases (addiction, bipolar disorder, obsessive compulsive disorder, depression, anxiety, autism, schizophrenia, and attention deficit hyperactivity disorder)." (PMID 29617307, 2018). "Our key results show that baculovirus-produced non-mammalian GDNF and GFRα1 stimulate human RET phosphorylation as well as signal through the MAPK/ERK cascade to promote the survival of dopaminergic neurons affected by Parkinson’s disease." (PMID 28467503, 2017).
renal agenesis (5 papers, 2018 to 2022). Renal agenesis (RA) is a form of renal tract malformation characterized by the complete absence of development of one or both kidneys (unilateral RA or bilateral RA respectively), accompanied by absent ureter(s). "We report two Saudi Arabian consanguineous families with CAKUT phenotypes that included renal agenesis caused by missense variants in GFRA1 and NPNT, confirming the role of these two genes in human kidney development." (PMID 36292572, 2022). "Another study demonstrated that stillborn fetuses with renal agenesis or severe dysplasia had a high positive rate (30%) of disease-causing mutations, although only RET, GDNF, and GFRA1 genes were evaluated." (PMID 32164334, 2020). "Although the knock-in mice expressed the transmembrane GFRα1 at normal levels, homozygous mice showed several phenotypes that are characteristic of null mice lacking GFRα1, including renal agenesis and loss of enteric neurons." (PMID 32737575, 2020). "Indeed, mouse models with null mutations in Ret or Gfrα1 demonstrated that signaling through GDNF-RET-GFRα1 is critical for kidney development, as these mice also present renal agenesis or severe renal hypoplasia." (PMID 30483151, 2018).
colorectal cancer (3 papers, 2016 to 2022). A primary or metastatic malignant neoplasm that affects the colon or rectum. "Increased expression of GDNF enhances β1 integrin expression via signaling through RET/GFRα1 in colorectal cancer cell lines, thus strongly influencing adhesion to and invasion of the extracellular matrix (ECM)." (PMID 35582425, 2022). "Further research showed that GFRα1 enhances proliferation probably by activating the AKT and ERK pathways; thus, GFRα1 might be a marker for poor prognosis in colorectal cancer." (PMID 35582425, 2022). "Similarly, in colorectal cancer cell lines, β1 integrin expression is enhanced by increased GDNF expression via signaling through RET/GFRα1, notably influencing adhesion to and invasion of the ECM." (PMID 35582425, 2022).
hepatocellular carcinoma (3 papers, 2017 to 2021). A malignant tumor that arises from hepatocytes. "In contrast, in hepatocellular carcinoma, the higher expression of GFRA1 was significantly correlated with good prognosis of patients." (PMID 33175846, 2020).
Hirschsprung disease (3 papers, 2018 to 2024). Hirschsprung disease (HSCR) is a congenital intestinal motility disorder that is characterized by signs of intestinal obstruction due to the presence of an aganglionic segment of variable extent in the terminal part of the colon. "Collectively, the results imply that mutation in GDNF, NRTN or RET reduce the affinity for GFRA1 interaction, resulting in Hirschsprung’s disease." (PMID 29617307, 2018). "Meanwhile, ablation of GFRA1 may cause a Hirschsprung’s disease phenotype." (PMID 33175846, 2020). "RET and GFRα-1 are the responsible genes for Hirschsprung disease, from which severe cases of IGD suffer." (PMID 38225934, 2024). "Although a GFRA1 mutation has not been found in Hirschsprung’s patients, Hirschsprung’s disease has been observed in heterozygous GDNF+/− mice." (PMID 29617307, 2018).
lymph node metastasis (3 papers, 2013 to 2020). "Increased GFRα1 expression has been previously reported in MC and its expression is associated with certain clinicopathologic features such as lymph node metastases." (PMID 23351331, 2013). "We have however described a clear metastasis promoting role for ARTN in ER negative MC consistent with the association of GFRα1 and GFRα3 expression with lymph node metastasis observed in this study." (PMID 23351331, 2013).
neuroblastoma (3 papers, 2014 to 2023). Neuroblastoma (NB) is the most common solid, extracranial childhood tumor. "Given that SORL1, GFRA1/2, ERBB2, are poorly or not expressed in SH-SY5Y neuroblastoma cells according to the Human Protein Atlas (last accessed on 12 September 2023), we made no attempt to model this trophic pathogenesis cascade in vitro." (PMID 37830614, 2023).
acromegaly (2 papers, 2020 to 2021). Acromegaly is an acquired disorder related to excessive production of growth hormone (GH) and characterized by progressive somatic disfigurement (mainly involving the face and extremities) and systemic manifestations. "Moreover, GFRα1 expression together with its ligand GDNF-remains relevant in somatotroph derived tumors causing acromegaly." (PMID 33071961, 2020). "It is known that GDNF is expressed by normal somatotrophs together with GFRα1 and its expression is preserved in somatotroph adenomas." (PMID 33071961, 2020). "Within the adenopituitary, somatotrophs express both RET and GFRα1, together with GDNF and this is maintained in somatotroph-derived pituitary tumors causing acromegaly." (PMID 33071961, 2020). "It has been previously shown that GFRα1 is expressed by somatotroph cells and acromegaly tumors." (PMID 33071961, 2020). "We performed immunohistochemistry for RET (total RET, HPA008356), GDNF and GFRα1 comparing five sporadic (Sp GH) and five AIP+ somatotroph adenomas." (PMID 34588620, 2021).
breast tumors (2 papers, 2012 to 2018). "Interestingly, the expression of genes (GFRA1, ID1, ABCG2) implicated in the regulation of hematopoietic progenitor cells was found to be elevated in bone metastases compared with the primary breast tumors that had relapsed to bone." (PMID 23174366, 2012). "In this study, we demonstrate that GFRA1 may serve as an ideal TAA for ADC-targeting because of its minimal expression in normal tissue and its overexpression in subsets of therapeutically challenging breast tumor types." (PMID 29796165, 2018).
cognitive decline (2 papers, 2015 to 2023). "An intronic variant rs2694777 in the GDNF family receptor alpha 1 gene (GFRA1) is among the common variants with suggestive association with rate of cognitive decline as measured by rate of change in CDR-SB (P = 1.2 x 10−5 European ancestry sample set and P = 6.77 x 10−6 in all races)." (PMID 26252872, 2015). "GFRA1 gene, which encodes GDNF family receptor alpha 1, a member of the GDNF receptor family, is among the few genes with suggestive association to rate of cognitive decline in the LMCI subgroup." (PMID 26252872, 2015). "Based on this evidence, we aimed to explore whether Gdnf-GFRα1 expression contributes to cognitive decline in the F1 and F2 generations of mouse dams exposed to lipopolysaccharide (LPS) during late gestation, and to evaluate also the potential interference effect of pro-inflammatory cytokines." (PMID 37055728, 2023).
cryptorchidism (2 papers, 2011 to 2025). The failure of one or both testes of a male fetus to descend from the abdomen into the scrotum during the late part of pregnancy. "We induced cryptorchidism in mice carrying GFRa1-EGFP, which is highly expressed in SSCs." (PMID 39745222, 2025).
depression (2 papers, 2017 to 2018). "In contrast, the protein levels of GDNF and its receptor GFRA1 were reduced in depression." (PMID 29617307, 2018).
diverticular disease (2 papers, 2015 to 2017). A complex disorder characterised by mucosal outpouchings (diverticulae) of the colonic wall which can become infected and inflamed leading to diverticulitis, perforation and bleeding. "As myenteric plexus are known to be the main source of GDNF receptor expression, immunopositive signals of RET and GFRα1 were investigated in colonic myenteric ganglia of patients with diverticulosis and DD." (PMID 28152033, 2017). "In addition, fluorescence intensity of GFRα1 is significant decreased to 61% ± 6% of the control group for diverticulosis and to 60% ± 9% for DD." (PMID 28152033, 2017). "Furthermore the mRNA expression of the corresponding receptor GFRA1 dropped down to 48% ± 6% of control values in patients with diverticulosis and to 58% ± 8% of control values in DD." (PMID 28152033, 2017). "Samples of tunica muscularis (TM) and laser-microdissected myenteric ganglia from patients with diverticulosis, DD and controls were analyzed for mRNA expression levels of GDNF, GFRA1, and RET by RT-qPCR." (PMID 28152033, 2017). "Confirmatory to mRNA expression, we observed a significant reduction in the myenteric protein expression of both GDNF receptors, GFRα1 and RET and in both patients with asymptomatic diverticulosis and DD, as quantified with fluorescence-immunohistochemistry." (PMID 28152033, 2017). "Although no myenteric morphometric alterations were found in patients with diverticulosis, GDNF, GFRA1 and RET mRNA expression was down-regulated in the TM of patients with diverticulosis as well as DD." (PMID 28152033, 2017). "Myenteric immunoreactivity of the receptors GFRα1 and RET was decreased in both asymptomatic diverticulosis and DD patients." (PMID 28152033, 2017). "Furthermore GFRA1 and RET myenteric plexus mRNA expression of patients with diverticulosis and DD was down-regulated, whereas GDNF remained unaltered." (PMID 28152033, 2017). "Since enteric muscle layers and neuronal tissue vary in mRNA expression levels of GDNF and its corresponding receptors, we performed site-specific mRNA expression analysis of RET, GFRA1 and GDNF of RNA isolated from myenteric ganglia of patients with diverticulosis and DD." (PMID 28152033, 2017). "Although no morphometric alterations of the ENS was found in patients with symptomless diverticulosis, decreased mRNA expression of GDNF and mRNA expression and fluorescence-intensity of its corresponding receptors GFRα1 and RET were found not only in DD but also in asymptomatic diverticulosis." (PMID 28152033, 2017). "Quantitative analysis of immunopositive RET and GFRα1 signals in the myenteric plexus of patients with diverticulosis, DD and controls revealed a significant drop-down in fluorescence intensity of RET to 38% ± 5% for diverticulosis and to 46% ± 4% for DD, when compared to controls." (PMID 28152033, 2017). "Thus, we performed a consensus-based morphometric analysis of the myenteric plexus and investigated the expression levels of GDNF and its receptors GFRα1 and RET in the tunica muscularis and myenteric plexus of patients with diverticulosis, DD, and controls at gene and protein level." (PMID 28152033, 2017).
laryngeal squamous cell carcinoma (2 papers, 2014 to 2020). A squamous cell carcinoma that arises from the larynx. "In laryngeal squamous cell carcinoma, the expression of GFRα1 and ARTN, another GFL member, was associated with more advanced pTNM stage." (PMID 32084217, 2020).
leukaemia (2 papers, 2021 to 2023). "In domestic animals, some markers such as GDNF family receptor alpha-1 (GFRα-1), Promyelocytic leukaemia zinc finger (PLZF), Thy-1 Membrane Glycoprotein (THY1), and Ubiquitin C-terminal hydrolase 1 (UCHL1) have been used to enrich and identify the undifferentiated spermatogonia." (PMID 37569546, 2023). "Transplantation of EL4 cells confirmed their tumorigenicity potential as tissuehistological examination revealed that the normal structure of the tubules haddisappeared, and the leukemia cells had penetrated the interstitial tissue.SSC was confirmed by expression of Plzf, Gfrα-1 and Oct4by PCR." (PMID 34837682, 2021).
Myocardial fibrosis (2 papers, 2023). "For DCTPP1 and GFRA1, a PubMed search did not identify any publications linking either protein with HDL-C, myocardial fibrosis, or myocardial scarring." (PMID 37790448, 2023).
Obesity (2 papers, 2022 to 2024). Accumulation of substantial excess body fat. "Gfra1, Or56b2j, Serpine2, and Tecrl were the only genes previously annotated with obesity-related traits." (PMID 38483771, 2024).
pancreatic adenocarcinoma (2 papers, 2020). "In human pancreatic adenocarcinoma, soluble GFRα1 was shown to be released from nerves and interacted with soluble GDNF to enhance perineural invasion, an event that is also observed in HNSCC." (PMID 32084217, 2020). "In contrast, the level of both APE1 and GFRα1 expression was significantly increased in pancreatic adenocarcinoma compared to adjacent normal cells." (PMID 32438692, 2020).
rectal cancer (2 papers, 2016 to 2017). A primary or metastatic malignant neoplasm that affects the rectum. "In addition this study showed that the methylation status of GFRA1 or GSTM2 was associated with rectal cancer." (PMID 27566576, 2016). "And methylation status of GFRA1 could be used as potential biomarkers for the screening of rectal cancer." (PMID 29037220, 2017). "Furthermore, the rectal cancer samples showed a significantly greater level of hypermethylated GFRA1 and GSTM2 when compared with the normal samples (P<0.05)." (PMID 27566576, 2016). "MS-HRM of two hypermethylated genes (GFRA1 and GSTM2) were conducted to validate an additional 44 pairs of rectal cancer and normal tissue samples." (PMID 27566576, 2016). "The findings of the present study for hypermethylation of GFRA1 and GSTM2 may provide an explanation for their low-expression in rectal cancer." (PMID 27566576, 2016). "We demonstrated that the methylation status of GFRA1 and GSTM2 could be used as potential biomarkers for the screening of rectal cancer." (PMID 27566576, 2016).
schizophrenia (2 papers, 2011 to 2017). A major psychotic disorder characterized by abnormalities in the perception or expression of reality. "A recent study found evidence for genetic associations between GFRA1 and 3 and schizophrenia, as well as evidence for GFRA2 variants modulating the therapeutic response to clozapine." (PMID 29066960, 2017). "GFRA1 is a receptor of the neurotrophin GDNF which has been widely investigated in mood disorders (MDD and bipolar disorder), schizophrenia and treatment responses)." (PMID 21750702, 2011).
virus infection (2 papers, 2020). "Western blot analysis at the time of virus infection confirmed that the specific siRNA pool dramatically reduced GFRα1 protein expression compared to untreated cells." (PMID 33233403, 2020). "At later stages of infection, VZV downregulated various other types of cell surface receptors, including the oxytocin receptor (OXTR), GDNF family receptor alpha-1 (GFRA1) and the poliovirus receptor (PVR; CD155), suggesting a more broad effect of virus infection on cell surface receptors." (PMID 32547533, 2020).
Anxiety (1 paper, 2021). Intense feelings of nervousness, tension, or panic often arise in response to interpersonal stresses. "Third, acute loss of GFRα1 in adult mHb neurons reduces anxiety-like behavior and potentiates context-based fear responses, phenocopying the effects of lesions to mHb afferents from the posterior septum." (PMID 34748545, 2021). "Our behavioral studies in adult mice following acute loss of GFRα1 in mHb neurons revealed an unexpected requirement for this receptor in normal anxiety-like behavior and conditioned fear responses." (PMID 34748545, 2021). "Finally, acute loss of GFRα1 in adult mHb neurons reduced anxiety-like behavior and potentiated context-based fear responses, phenocopying the effects of lesions to septal projections to the mHb." (PMID 34748545, 2021). "Significantly, loss of GFRα1 in the mHb resulted in changes in the molecular composition of mHb AMPA receptors that reduced their Ca2+ permeability, as well as alterations in fear and anxiety behaviors that paralleled those observed after lesion of the septohabenular pathway." (PMID 34748545, 2021). "In the elevated plus maze, KO mice entered more times and spent significantly longer time in the open arms than WT and Het animals, suggesting reduced anxiety-like behavior in adult mice lacking GFRα1." (PMID 34748545, 2021). "This study explores the role of GFRα1 in habenular neuron function, revealing that it regulates the maintenance of adult synapses in the septohabenular pathway, AMPA-mediated glutamatergic signaling, and fear and anxiety behaviors." (PMID 34748545, 2021).
atherosclerosis (1 paper, 2024). A disease characterized by the build-up of fatty material and calcium deposition in the arterial wall resulting in partial or complete occlusion of the arterial lumen. "We were able to confirm three additional proteins associated with CIMT using our age-sex adjusted model namely GFRA1, IGFBP2 and GHR, which have been all reported to be linked to CVD, mortality, and atherosclerosis." (PMID 38811951, 2024).
benign breast disease (1 paper, 2013). "We first utilized ISH to determine the expression of GFRα1, GFRα3 and SDC3 mRNA in mammary tissue from benign breast disease (BBD) and MC." (PMID 23351331, 2013).
bile duct carcinoma (1 paper, 2020). "Despite the absence of GFRα1 expression in the normal bile duct, GFRα1 clearly is expressed in bile duct carcinoma, indicating that carcinogenesis leads to the aberrant expression of GFRα1." (PMID 32438692, 2020).
brain tumours (1 paper, 1999). "We investigated a panel of 36 independent cases of mainly advanced sporadic brain tumours for the presence of mutations in GDNF and GFRα-1." (PMID 10408842, 1999). "Our data suggest that intragenic point mutations of GDNF or GFRα-1 are not a common aetiologic event in brain tumours." (PMID 10408842, 1999).
cervical cancer (1 paper, 2016). A primary or metastatic malignant neoplasm involving the cervix. "QMSP was designed for 5 genes (GFRA1, SLC6A5, SOX1, SOX14, TBX20) and their diagnostic potential was evaluated on scrapings from a large series of cervical cancer patients (n=125: 57 ADC and 68 SCC) and controls with similar age." (PMID 27738327, 2016). "Of the 53 differentially methylated candidates that were found in both ADC and SCC, 20 genes were described previously in literature as being more frequently methylated in cancer, and 6 genes in (squamous-cell) cervical cancer (SOX1, SOX14, ONECUT1 and WT1) or high-grade CIN (GFRA1, SOX1 and TBX20)." (PMID 27738327, 2016).